CD4 (CD4 molecule)
Diseases named in the same sentence as CD4 in open-access papers (continued):
Sharing a sentence is not in itself a finding about the gene and the disease.
psoriasis (continued). "More recently, CD8+ cells have been also recognized to produce these cytokines in both psoriasis and atopic dermatitis, highlighting the importance of reducing both CD4+ and CD8+ infiltration in skin lesions." (PMID 38067173, 2023). "CitLL37 induced IL-10-producing CD4+ T cells in patients with psoriasis, exclusively, and IL-10 was detected in the culture supernatants after stimulation of MNCs from patients with psoriasis with LL37 as well as with citLL37." (PMID 38173716, 2023). "Regulator T cells (Tregs) and CD4+ memory T cells increased quickly in 25–66.7% of female and male psoriasis patients." (PMID 37763198, 2023). "CD4+ T helper (Th) cells play a crucial role in psoriasis pathogenesis, and the imbalance of Th subsets, including Th1/Th2 and Th17/Treg subsets, contributes to the immunopathology of psoriasis." (PMID 37773129, 2023). "The CD4+ T cells, helper T (Th) cells, can be differentiated to Th1, Th2, Th22/Th17 and Treg cells, play a central role in the pathogenesis of psoriasis." (PMID 37270497, 2023). "To investigate the impact of miR-125a-5p in regulating Th17/Treg cells in IMQ-induced psoriasis-like inflammation in vivo, we measured the proportions of Th17 cells and Tregs in CD4+ T cells of mice in the agomir-125a-5p group." (PMID 37773129, 2023). "One crucial aspect of CD4+ T-cell involvement in psoriasis and PsA is their differentiation into distinct effector subsets, particularly T-helper 17 (Th17) and T-helper 22 (Th22) cells." (PMID 37662940, 2023). "CD8+CD103+ TRM cells release psoriasis-associated cytokines such as IFN-γ, IL-17A, and IL-22, while CD4+CD103+ TRM cells and CD8+CD103- TRM cells don’t secrete these cytokines." (PMID 37942312, 2023). "This study focused on the status of circulating CD4+ T subsets and the clinical efficacy of low-dose IL-2 therapies in psoriasis." (PMID 37596509, 2023). "As both Th17 (CD4) and Tc17 (CD8) cells are important pathogenic cells in psoriasis, we examined the functional effects of the dNP2-ctCTLA-4 peptide on mouse CD4 and CD8 T cells in vitro." (PMID 37818377, 2023). "SCFAs such as butyrate that were heavily discussed surrounding AD also play a role in psoriasis via their induction of differentiation of thymic T regulatory cells and naïve CD4+ T cells into peripheral Tregs by histone deacetylase inhibition." (PMID 37623895, 2023). "Comparison of DNA methylation patterns in CD4+ T-cells from healthy controls with cells from “all” psoriasis patients (skin psoriasis and PsA) identified 883 DMPs (433 hypo-, 450 hypermethylated) affecting 548 genes." (PMID 37662940, 2023). "Given the recognized role of effector T-cells in the pathophysiology of psoriasis and PsA, the here presented study focused on examining DNA methylation patterns in CD4+ T-cells." (PMID 37662940, 2023). "CitLL37, but not native LL37, induced IFN-γ-production by T cells and B cells from psoriasis patients, as well as IL-10-production by the patients’ CD4+ T cells." (PMID 38173716, 2023). "This study revealed distinct DNA methylation profiles in CD4+ T-cells that distinguish psoriasis patients from healthy individuals and revealed additional differences between patients with skin psoriasis and PsA." (PMID 37662940, 2023). "During the inflammatory process of psoriasis, naïve CD4+ T cells differentiate into Th1 or Th17 cells upon stimulation with various cytokines, promoting the activity of the adaptive immune system." (PMID 37649889, 2023). "CD4 CD25− cells separated from PBMCs of psoriasis patients treated with PUVA and activated with anti-CD3/CD28-bound beads, were cultured with or without CD4 CD25+ T-cells." (PMID 36901778, 2023). "This technique also helped to identify a CD4+ Treg cell population in psoriasis that was noted by the expression of FOXP3, TIGIT, CTLA4, IL2RA (CD25), and IKZF2." (PMID 37270497, 2023). "Research has shown that CD4+ helper T cells are present in the dermal skin of individuals with psoriasis." (PMID 37942312, 2023).
psoriasis (continued). "In a murine model of psoriasis, isolated CD4+CD25+ Tregs showed decreased cell proliferation abilities and a weakened immunosuppressive function, with significantly increased levels of PI3K pathway effectors, pAKT and pFoxo1." (PMID 37892710, 2023). "Here the authors establish a role for IL-26 in the generation of IL-17A producing Th17 CD4+ T cells and suggest it involves epithelial cross talk in skin lesions of psoriasis patients." (PMID 37391412, 2023). "Lastly, we quantified the levels of mast cell activation, which contributes to psoriasis pathogenesis and constitutes an important source of VEGF‐A20, 41, 42; and key immune mediators in the pathogenesis of psoriasis, CD4+ and CD8+ cells." (PMID 37799359, 2023). "RORγt, mainly expressed in lymphocytes, can regulate the differentiation of CD4+ T cells into Th17 cells, which is closely related to psoriasis." (PMID 38008779, 2023). "CD4+ T cells from patients with guttate psoriasis induce more apoptosis of keratinocytes and promote keratinocyte proliferation, which contributes to the initiation of the disease." (PMID 35967358, 2022). "The proportion of Tr1 (CD49b+ LAG-3+) cells in CD3+ CD4+ T-cells in the blood of psoriasis patients was decreased in psoriasis patients compared with healthy individuals, and the proportion of Tr1 cells decreased as PASI increased." (PMID 36110854, 2022). "We found that the proportion of IL-4+ in CD4+ (Th2) cells was significantly higher in psoriasis patients than in HCs." (PMID 35927231, 2022). "Further exploration suggested its efficacy mainly through inhibiting TH17 differentiation from CD4+ T cells, thus attenuating the IL-17 signaling pathway that leads to psoriasis." (PMID 35669784, 2022). "The elevated overall IL-21 secreted by CD4+ T cells and Th17 cells in the serum of psoriasis patients is significantly correlated with a progressive PASI score." (PMID 35203707, 2022). "There is compelling evidence that CD4+Foxp3+ regulatory T cells (Tregs) are indispensable in the inhibition of autoimmune inflammatory responses, including psoriasis." (PMID 35464441, 2022). "Upregulation of LAT1 in CD4+ T cells was observed in imiquimod-induced psoriasis, another skin inflammation model." (PMID 35454142, 2022). "HIV infection is associated with a depletion of CD4+ lymphocytes and HIV associated psoriasis tends to present in patients with low CD4+ cell counts and an overall reduced immune status." (PMID 35225942, 2022). "JPH203 treatment and Slc7a5 gene disruption in CD4+ T cells alleviated disease progression with cytokine production in a psoriasis mouse model." (PMID 35454142, 2022). "We indicated that MUP attenuated IMQ-induced psoriasis-like inflammation by reducing infiltrations of CD4+T cells, CD8+T cells, Ly6G+ neutrophils in the lymphoid nodes and increasing CD207+ LCs in the epidermis." (PMID 36419191, 2022). "As for particular cell involvement, Th17 lymphocytes and pro-inflammatory CD4+ T cell lineage, are an important link in psoriasis, as described in the introduction, but apparently also in PD." (PMID 36226313, 2022). "Treatment with commissioned Longkui Yinxiao Tablet for 8 weeks resulted in higher CD4+/CD8+ and CD4+ levels in the psoriasis treatment group and lower CD8+ and cytokines TNF-α, IL-6, and IL-17 levels compared with the control group." (PMID 36052142, 2022). "Treatment with compound A ameliorated psoriasis skin lesions and suppressed the number of CD4+IL-17A+ T cells in the lymph nodes and the spleen in an FFA4-dependent manner." (PMID 35562873, 2022). "Previously, psoriasis immunopathogenesis has been viewed as the imbalance between CD4+ T-helper 17 (Th17) cells and regulatory T-cells (Tregs)." (PMID 36110854, 2022). "As for circulating lymphocytes, CD4+/IL-17+ and CD4+/IL-22+ T-lymphocytes have been investigated with great interest because of their role in skin infection and in the skin of patients with psoriasis." (PMID 35722498, 2022).
psoriasis (continued). "In contrast to the increase of Th1 and Th17 cells, the level of CD4+ Foxp3+ T cells was reduced in psoriasis-induced mice." (PMID 36591260, 2022). "In psoriasis, with the presence of IL-6 and transforming growth factor-β, CD4+ T cells will undergo differentiation into Th17." (PMID 35203707, 2022). "In the imiquimod induced psoriasis mice model, CD4+ and TCR γδ T cells are believed to be major sources of IL-17 and IL-22." (PMID 35629363, 2022). "TIGIT expression levels on CD4+ T cells of psoriasis vulgaris (PV) patients are significantly reduced and it is negatively correlated with psoriasis area and severity index." (PMID 35720417, 2022). "Functional inhibition of Th1 and Th17 cells by ndSTAT1-TMD in the psoriasis-induced mice substantially restored the level of CD4+ Foxp3+ T cells." (PMID 36591260, 2022). "To appraise the effects of CB2R on IMQ-induced local and systemic inflammation, we used IHC to observe the infiltration of CD4+ T cells, which are the main source that induce differentiation into various subtypes of T cells in psoriasis." (PMID 35173615, 2022). "Antigen-presenting cells produce IL-23, supporting the development of CD4+ memory T cells responsible for the inflammatory state in psoriasis, secreting IL-17." (PMID 35886846, 2022). "In the present study, we found that CB2R KO contributed to the pathogenesis of psoriasis by promoting CD4+ T cell proliferation; upregulating Th17 cytokines, such as IL-17A, IL-23A, and IL-17C; and downregulating IL-10." (PMID 35173615, 2022). "First of all, we examined the therapeutic effect of aloperine on psoriasis, a skin lesion predominantly mediated by the CD4+ T-cells." (PMID 35721119, 2022). "Although the pathogenesis of psoriasis remains elusive, the imbalance of CD4+ T cell subsets has been demonstrated to be a critical pathogenic factor, which involves Th1 and Th17 cell expansion and Treg cell dysfunction." (PMID 33718413, 2021). "Our data demonstrate that GADD45a and GADD45b are upregulated in peripheral CD4+ T cells from psoriasis patients at basal conditions." (PMID 34272424, 2021). "In psoriasis, the IL-17+ CD4+ had higher levels of bound PLTs and anti-TNF-α drugs normalize the numbers, while in HIV there are more lymphocytes-PLTs aggregates and are associated to D-dimer levels, increasing the CV risk." (PMID 33868242, 2021). "Inflammatory diseases including psoriasis are manifested as an overreaction of inflammation and its skin lesions are enriched with CD4+ T cells such as Th17 and high levels of inflammatory factors." (PMID 34220863, 2021). "Recent studies have found that the CD4 T cell subset circulating cTfh cells were related to the development of many diseases including psoriasis." (PMID 34512732, 2021). "Circulating CD4+ T lymphocytes from patients with psoriasis were also shown to have increased levels of GADD45b mRNA and protein." (PMID 34272424, 2021). "Given an important role of the CD146 in the IL-23/IL-17 cytokine network and in psoriasis we studied the association of CD146 expression and CD4+ IL-17+ activated memory T cells in PsA, RA and OA patients, in the blood as well as in the synovial fluid (SF)." (PMID 34491483, 2021). "A higher number of CD69-positive CD4+ T cells were found in the psoriasis patients than in the healthy controls." (PMID 35186952, 2021). "Here we summarized the accessible knowledge of miR-210, miR-138, miR-21, miR-200a, and miR-146a that regulate CD4+ T cells in psoriasis." (PMID 33718413, 2021). "We found that CD8αα+T cells enhanced the proliferation of CD4+T cells in patients with psoriasis but inhibited its proliferation in healthy controls." (PMID 35663772, 2021). "There was a significant difference between the amount of CD4 + in the epidermis and the dermis in the control group (p < 0.05) and in people with psoriasis (p < 0.05)—the amount was higher in the dermis." (PMID 34769769, 2021).
psoriasis (continued). "Interesting that ozonated autohemotherapy (OAHT) treatment also elevated PPARγ expression in CD4+ T cells of patients with psoriasis and decreased patients’ PASI scores." (PMID 34445309, 2021). "The types of immune cell infiltration calculated by the expression of DMEGs hypermethylation genes in psoriasis tissues mainly included CD4 T cells, NK cells, DCs, and so on." (PMID 34512732, 2021). "Upregulated miR-210 and downregulated miR-138 work in concert to distort CD4+ T cell subsets balance, which is a crucial pathomechanism in psoriasis." (PMID 33718413, 2021). "Mechanistically, TGF-β/IL-23 induces hypoxia-inducible factor-1α (HIF-1α), which recruits the histone acetyltransferase P300 to the miR-210 promoter region, thereby enhancing miR-210 expression in CD4+ T cells from psoriasis patients." (PMID 33718413, 2021). "CD4 T cells were key components of the immune system and had been shown to play an important role in the pathogenesis of psoriasis." (PMID 34512732, 2021). "RT-PCR assays showed that CD4+ T cells from psoriasis patients expressed higher levels of GADD45a compared to control subjects." (PMID 34272424, 2021). "Recently, low PPARγ expression in CD4+ T cells from 12 psoriasis patients than in healthy controls was reported." (PMID 34445309, 2021). "Our work supports previous data showing that cathelicidin is recognised by some CD4+ T cells as an autoantigen during psoriasis, and those T cells which recognise cathelicidin produce more IL-1758." (PMID 33627652, 2021). "Upregulated miR-200a in CD4+ T cells induce immune dysfunction through increasing Th17/Treg ratio and pro-inflammatory cytokine production in psoriasis patients." (PMID 33718413, 2021). "Previous studies have found the activation and aggregation of macrophages by immunostaining psoriatic lesions, and once macrophages are activated, they can induce psoriasis-like lesions independently of CD4+ T cells." (PMID 33613635, 2021). "In our previous study, TCDD was found to regulate the expression of AhR-related factors and cytokines in peripheral blood mononuclear cells (PBMCs) as well as CD4+ T cells from patients with psoriasis." (PMID 34884515, 2021). "The deletion of Treg cells in mice with imiquimod induced psoriasis phenotypes leads to increased infiltration of γδ, CD4+ and CD8+ T cells, the increased presence of IL-17 and TNF-α, as well as increased severity of skin lesions." (PMID 34639182, 2021). "In this study, for the first time, we decided to investigate CD137 expression in psoriasis skin lesions by immunohistochemical method and evaluate the relationship of the expression with CD4/CD8 ratio." (PMID 33936220, 2021). "The IL-23/IL17 axis is the main immune pathway in the pathogenesis of psoriasis, and the main immune cells involved in psoriasis include CD4+T cells, DCs, neutrophils, macrophages, and Tfh." (PMID 33732554, 2021). "Psoriasis is a chronic immune-mediated skin disease, whose hallmarks include keratinocyte hyperproliferation and CD4+ T cell subsets imbalance." (PMID 33718413, 2021). "Patients with psoriasis manifest functional defects in CD4+CD25+ forkhead box protein 3 (Foxp3)+ regulatory T cells (Tregs), which suppress the excess immune response and mediate homeostasis." (PMID 34501328, 2021). "Thereafter, coculture of CD8αα+T cells with autogenous CD4+T cells was performed to investigate the function of CD8αα+T cells in patients with psoriasis." (PMID 35663772, 2021). "Consistent with previous studies, CD8αα+T cells from healthy subjects suppressed the proliferation of auto‐CD4+T cells but promoted its proliferation in patients with psoriasis." (PMID 35663772, 2021). "The expression of miR-210 is increased in CD4+ T cells from patients with psoriasis and psoriasis mouse models." (PMID 33718413, 2021).
psoriasis (continued). "Skin lesions from patients with psoriasis exhibit epidermal hyperplasia and infiltration with neutrophils, T CD4 + and T CD8 + cells, B cells, dendritic cells and mast cells, type 3 innate lymphoid cells (ILC3) and γδ T cells." (PMID 33692806, 2021). "Our results showed similar expression patterns and high percentages of Th17 cells identified either as CD4+ RORγt+ or CD4+ CD161+ cells in the skin lesions of psoriasis patients." (PMID 32801996, 2020). "In our study, it was shown that GA inhibited the phosphorylation of mTOR and increased the CD4+FoxP3+ Treg frequency in spleen and lymphonodus in mice with imiquimod-induced psoriasis." (PMID 32908937, 2020). "Intracellular cytokine staining revealed heightened production of IFN-γ in both the CD8+ T and conventional CD4+ (Tcon) compartments, which was markedly elevated over that observed in psoriasis skin." (PMID 32841223, 2020). "The discovery of a novel Th17 cell subset characterized by the production of IL-17, a highly proinflammatory cytokine that induces severe autoimmunity, shifted the model of psoriasis pathogenesis and conferred a central role to this type of CD4+ T cell." (PMID 32224981, 2020). "In summary, our study provided evidence that MDSCs play a proinflammatory role in IMQ-induced psoriasis-like skin inflammation and regulating the infiltration of CD4+ T-cells." (PMID 32684837, 2020). "S100A7 is induced by calcium, vitamin D, retinoic acid, bacterial products, TNF-α, IL-17A and IL-22, and is involved in the pathogenesis of psoriasis via its chemotactic activity for neutrophils and CD4+ T lymphocytes." (PMID 32947991, 2020). "Our recent research has also shown the increased production of ROS in memory CD4+ T cells of psoriasis patients." (PMID 33354282, 2020). "Already in the 1990s, several attempts to treat psoriasis through systemic infusion of monoclonal antibodies depleting CD3+ or CD4+ T cells showed reduced severity of psoriasis in patients." (PMID 32757303, 2020). "Immune imbalance of CD4+ T subset is considered to be a critical factor in the pathogenesis of psoriasis." (PMID 32398953, 2020). "CD3+ skin T cells of classical psoriasis showed instead an enrichment of both CD4+ and CD8+ subpopulations." (PMID 31577850, 2020). "Subsequently, the role of CD4+ T cells in psoriasis has been intensely investigated, revealing that psoriasis-like dermatitis develops in mice transplanted with CD4+ T cells from psoriasis patients." (PMID 32917058, 2020). "To validate our CHi-C data, we overlaid the interactions with a published expression quantitative trail locus (eQTL) dataset, in which the lead psoriasis SNP had been colocalised with the lead eQTL SNP in CD4+ T cells and monocytes." (PMID 32366252, 2020). "Recently, vitamin D was reported to suppress the expression of hBD2, hBD3, IL-17A/F and IL-8 in psoriasis plaques and induce CD4+CD25+ regulatory T cells." (PMID 32947991, 2020). "CD4+ T cell incorporation and migration in the skin model has also been used for studying psoriasis." (PMID 32509598, 2020). "We also found that the proportion of Treg cells was negatively correlated with that of Th17 cells, while the proportion of Th1 cells (CD4+IFN-γ+) was increased in psoriasis patients." (PMID 31440249, 2019). "Our data showed that peripheral CD4+ T cells from psoriasis patients expressed lower levels of CD47 compared to healthy controls." (PMID 31214201, 2019). "CD4+ T cells were isolated from PBMCs derived from the psoriasis patients and healthy individuals, then treated with or without IL-21 for 3 days." (PMID 31440249, 2019). "Herein, fisetin significantly ameliorated psoriasis-like disease features, and decreased the production of IL-17 by CD4+ T lymphocytes co-cultured with FTRHSP." (PMID 31540162, 2019). "This would be a similar mechanism to other autoimmune/inflammatory diseases such as psoriasis, which shows impaired suppression of CD4+CD25− T cells." (PMID 30798353, 2019).